IL6 (interleukin 6)
Diseases named in the same sentence as IL6 in open-access papers (continued):
Sharing a sentence is not in itself a finding about the gene and the disease.
empyema (4 papers, 2019 to 2024). An accumulation of pus in a body cavity, usually the pleural space. "Interestingly, baseline levels of TNF-α, IL-6, and IL-8 were in the ranges previously observed for rabbit models of chemically induced pleural injury and advanced 7 d empyema." (PMID 39201465, 2024). "Notably, while levels of PAI‐1, TGF‐β, TNF‐α, IL‐6, and IL‐8 were elevated in both models, they were higher (p < 0.05) in empyema." (PMID 33991465, 2021). "Moreover, levels of PAI-1, TGF-β, TNF-α, IL-6, IL-8 observed in pleural fluids of human patients with empyema and with parapneumonic effusions were also higher than those in the transudative pleural fluids and were comparable to the levels observed in the rabbit empyema model (Table A1)." (PMID 37242740, 2023). "The AUC values for distinguishing CPPE and empyema from UPPE were 0.775 for serum NGAL, 0.765 for serum calprotectin, and 0.766 for serum CRP, and 0.717 for serum IL-6." (PMID 31215423, 2019). "The levels of CRP and IL-6 were significantly higher in pleural fluid from patients with CPPE and empyema." (PMID 31215423, 2019). "In the CPPE and empyema patients, the serum CRP and serum IL-6 levels were significantly elevated, and these results were consistent with those of previous reports." (PMID 31215423, 2019).
epididymitis (4 papers, 2021 to 2025). Inflammation of the epididymis. "The LPS-induced mouse epididymitis model was validated by significantly increased expression of IL-6 and TNF-α in both the caput and cauda epididymis at 72 hours post-injection." (PMID 41445755, 2025). "As an inflammatory mediator, the content of NFKBIA may decrease, while cytokines such as IL6 may increase in the epididymitis." (PMID 34153045, 2021). "Moreover, the expression level of IL-6 and IL-10 was upregulated 30-fold and 5-fold in CE compared with the controls, which was also proved to be the epididymitis characteristics through mouse model induced by Gram-negative (LPS) and Gram-positvie (LTA) stimulation." (PMID 35634321, 2022). "In the vivo experiments, levels of the proinflammatory cytokines IL-1α, IL-6, IL-17A, TNF-α, IL-1β, MCP-1, and GM-CSF, mRNA for MyD88 related genes, and the percentages of monocyte-derived DCs (Mo-DCs) were significantly elevated in mice with epididymitis." (PMID 37175545, 2023).
epithelial dysplasia (4 papers, 2012 to 2025). "Specifically, IL-1 beta, IL-6, and IL-8 can induce epithelial dysplasia." (PMID 40805215, 2025). "Overall, epithelial dysplasias showed non-statistically significant increased positivity for IL-6 compared to hyperplasias and OSCCs." (PMID 26595830, 2016). "In the present study, the non-statistically significant increased IL-6 expression in epithelial dysplasias compared to hyperplasias and normal mucosa suggests a possible role of this molecular pathway in oral carcinogenesis." (PMID 26595830, 2016).
febrile seizures (4 papers, 2011 to 2024). "In conclusion, our data brought a novel observation that the presence of a G allele or GG genotype at the −174 and the GG genotype at the −597 positions of the promoter region of the interleukin-6 gene constitute risk factors for developing febrile seizures in Egyptian children." (PMID 26960986, 2016). "Another clinical study demonstrated that febrile convulsions increase the levels of cytokines IL-1β, IL-6, and TNF-α in cerebrospinal fluid." (PMID 39315097, 2024). "The association between plasma interleukin-6 (IL-6) levels and the development of febrile seizures (FS) has been reported in multiple previous studies, which showed significantly higher serum IL-6 levels in FS patients than in control patients." (PMID 31574823, 2019). "Comparisons of IL-6 levels among afebrile and febrile controls, and the four seizure groups showed significantly higher IL-6 levels in first and recurrent attack febrile seizure patients (p < 0.05)." (PMID 21989210, 2011).
fibrous dysplasia (4 papers, 2014 to 2025). A genetic, non-inheritable disorder caused by osteoblastic differentiation defects that result in the replacement of bone marrow and trabecular bone by fibrous stroma and immature bone. "The use of bisphosphonates and IL-6 inhibitors has been explored to be useful in the treatment of fibrous dysplasia, but more research is warranted." (PMID 25530967, 2014). "The use of bisphosphonates and IL-6 inhibitors may be useful in the treatment of fibrous dysplasia, but further studies are needed." (PMID 25530967, 2014).
focal segmental glomerulosclerosis (4 papers, 2016 to 2025). A renal disorder characterized by sclerotic lesions in the glomeruli. "Microphotographs of renal tissue revealed focal segmental glomerulosclerosis and intense tubular immunopositivity for IL-6 and TNF-α after 6 months of sustained cola drinking." (PMID 27340342, 2016). "Infiltrating immune cells perpetuated injury by stimulating collagen deposition and α-SMA expression viainterleukin-6 (IL-6)/signal transducer and activator of transcription 3 (STAT3)-mediated pathways, as shown in podocyte injury in focal segmental glomerulosclerosis." (PMID 40276370, 2025). "We demonstrated that citral (3,7-dimethyl-2,6-octadienal) isolated from L. cubeba inhibited the production of nitric oxide (NO), TNF-α, and IL-6 by reducing NF-κB activation and ROS production in LPS-activated RAW264.7 macrophages and improved focal segmental glomerulosclerosis in mice." (PMID 35967819, 2022).
Follicular Cyst (4 papers, 2014 to 2025). Cyst due to the occlusion of the duct of a follicle or small gland. "Increased IL-6 is associated with anovulatory situations in cows, such as ovulation failure, follicular persistence, and follicular cysts." (PMID 41044774, 2025).
Fulminant hepatitis (4 papers, 2012 to 2025). Acute hepatitis complicated by acute liver failure with hepatic encephalopathy occurring less than 8 weeks after the onset of jaundice. "Indeed, plasma IL-6 levels are significantly increased in patients with fulminant hepatitis and are indicative of a poor prognosis." (PMID 23166746, 2012). "In mice with fulminant hepatitis, TEC can protect the liver against inflammatory damage by downregulating TLR4, IL‐6, TNF‐α, iNOS, and COX‐2 expressions." (PMID 38722267, 2024).
G6PD deficiency (4 papers, 2021 to 2024). An X-linked genetic condition caused by alterations in the gene G6PD that result in moderately to severely decreased activity levels of the enzyme glucose-6-phosphate dehydrogenase. "Peripheral mononuclear cells produce lower levels of proinflammatory cytokines, IL-6 and IL-1β, under G6PD deficiency." (PMID 38049886, 2023). "On clinical assessment clinicians should consider the possibility of glucose‐6‐pyruvate dehydrogenase (G6PD) deficiency in COVID‐19 patients as this group of patients may have a dominance of high‐producing IL‐6 allele." (PMID 32986289, 2021). "To further understand the role of cytokines in the context of G6pd deficiency, we measured the expression of TNF-α, IFN-γ, IL-1β, IL-6, IL-12, TGF-β and IL-10 along with cytokine levels in serum and mRNA expression in spleen." (PMID 34456927, 2021). "Although, PWV increases with both age and higher glucose levels, after adjustment for age and glucose, differences in PWV and IL6 in diabetics with and without G6PD deficiency remained significant." (PMID 37741911, 2024). "This is the first study to demonstrate that G6PD deficiency in diabetics, but not non-diabetics, is associated with higher plasma IL6 levels and stiff arteries." (PMID 37741911, 2024). "In diabetics G6PD deficient subjects had significantly greater IL6 levels, and PWV compared to diabetic subjects without G6PD deficiency." (PMID 37741911, 2024).
gangrene (4 papers, 2014 to 2025). Death of tissue, usually in considerable mass and generally associated with loss of vascular (nutritive) supply and followed by bacterial invasion and putrefaction. "We found that a previous history of amputation, a higher Wagner grade, the presence of gangrene, and higher WBC, ESR, and IL-6 are associated with lower extremity amputation in patients with DFUs." (PMID 24948983, 2014). "Through a systematic analysis of 12 drugs and six key genes (IGF1, IL17A, ACE, FGF2, IL6 and TLR4), we have provided a new scientific perspective on gangrene prevention in diabetic patients." (PMID 40657379, 2025).
gastroparesis (4 papers, 2021 to 2025). Paralysis of the muscles of the stomach wall resulting in delayed emptying of the gastric contents into the small intestine. "Surprisingly, we found that the subjective cardinal symptoms of gastroparesis were inversely associated with levels of IL-6." (PMID 37189645, 2023). "The levels of several cytokines, including serum TNFα and IL-6, are elevated in gastroparesis patients." (PMID 37033595, 2023). "At baseline, patients with gastroparesis symptoms exhibited increased levels of interleukin-6 (IL-6) (46.64 to 53.01 pg/mL) and tumor necrosis factor-alpha (TNF) (22.18 to 7.46 pg/mL) (normal Interleukin-6 10.1 pg/mL and TNF 7.1 pg/mL, respectively)." (PMID 34584813, 2021).
Genetic obesity (4 papers, 2011 to 2015). "Similarly, the perigonadal adipose tissue of 8-week old obese KK-Ay mice, a model of genetic obesity, demonstrated elevated IL-6 gene expression levels." (PMID 22051061, 2011).
hemochromatosis (4 papers, 2020 to 2024). A disorder of iron metabolism characterized by a triad of HEMOSIDEROSIS; LIVER CIRRHOSIS; and DIABETES MELLITUS. "For example, in mice with hemochromatosis, IL-6/hepcidin signaling was activated and contributed to ferroptosis of mouse hepatocytes, which could be suppressed by the anti-inflammation drug auranofin." (PMID 35549778, 2022). "Estrogen reduced the ability of AUR to induce IL-6/hepcidin signaling in Huh7 cells, providing a mechanistic explanation for the ineffectiveness of AUR in female Hfe–/– mice (a mouse model of hemochromatosis)." (PMID 34977116, 2021).
hemophilia (4 papers, 2019 to 2022). Hemophilia is a genetic disorder characterized by spontaneous hemorrhage or prolonged bleeding due to factor VIII or IX deficiency. "IL-6 has been associated with bone/joint health (or rather, bone/joint pathology) in hemophilia mice and and IL-6 signalling blockage by using IL-6 receptor antagonist may be used as an adjunct to replacement hemostasis and an approach to minimize hemophilic joint degeneration." (PMID 31594977, 2019). "Theoretically, an anti-cytokine approach can be used to protect against bleeding in damaged joints; however, limited studies have shown that intervention of the cytokine network may serve as a novel therapeutic direction; this includes our previous study with anti-IL-6 in hemophilia A mice." (PMID 31892201, 2019).
hemorrhagic disease (4 papers, 2018 to 2025). Spontaneous or near spontaneous bleeding caused by a defect in clotting mechanisms (blood coagulation disorders) or another abnormality causing a structural flaw in the blood vessels (hemostatic disorders). "Early pro-inflammatory peaks (e.g., IFN-γ, TNF, IL-6) may drive vascular inflammation and tissue damage, contributing to severe clinical signs such as bleeding disorders, where endothelial injury and dysregulated coagulation cascades are involved." (PMID 41039483, 2025). "Consistent with hemorrhagic disease, negative control animals showed signs of liver damage as evidenced by increased levels of liver enzyme AST, and several key cytokines such as IL-1β, IL-6, IL-1Ra, MIP-1α, TNFα, IFN-γ, IL-2, and FGF-β." (PMID 30723475, 2018).
hepatoblastoma (4 papers, 2012 to 2024). Hepatoblastoma (HB) is a malignant hepatic tumor and is the most common pediatric liver cancer. "STAT3 and RELA/p65 formed a complex in HepG2 hepatoblastoma cells stimulated with IL-1 and IL-6, and NF-κB RELA/p65 homodimers were shown to cooperate with STAT3 in Hep3B cells in response to IL-1." (PMID 39641161, 2024). "In the present study, IL‐6 was suggested to be a growth factor secreted by macrophages that acts on hepatoblastoma cells." (PMID 35132816, 2022). "IL-6 suppresses the secretion and gene expression of thyroxine-binding globulin in the Hep G2 hepatoblastoma-derived cell line." (PMID 22672862, 2012). "IL‐6 was significantly induced cell proliferation in hepatoblastoma cell lines." (PMID 35132816, 2022). "However, notable induction of IL‐6 was induced by stimulation with CM from hepatoblastoma cell lines." (PMID 35132816, 2022). "Unstimulated macrophages and hepatoblastoma cell lines secreted low levels of IL‐6." (PMID 35132816, 2022). "miR-126 downregulation notably attenuated hepatoblastoma tumor growth and decreased the ratio of CD44+ CD90+ CD133+ cells and increased the expression of IL-6, Oct4, SRY, TGF-β, and β-catenin in tumor tissues of mice." (PMID 34746322, 2021). "Consistently, the contents of IL-6 and TGF-β1 in BMSC supernatants were significantly upregulated in the presence of EVs derived from hepatoblastoma cells." (PMID 34746322, 2021). "EVs derived from hepatoblastoma cells significantly increased the ratio of CD44+ CD90+ CD133+ cells and increased the expression of IL-6, Oct4, SRY, and TGF-β in bone marrow mesenchymal stem cells (BMSCs), while EVs with downregulated miR-126 reversed these phenomena." (PMID 34746322, 2021).
Hernia (4 papers, 2023 to 2025). "Longitudinal studies show that IL-6 rises within 6 h after hernia repair and peaks at 24 h, while oxidative markers peak earlier, suggesting that ROS generation is a trigger for subsequent cytokine cascades." (PMID 41440470, 2025). "In vitro, we investigated the effect of the hernia meshes on M0- and M1-like macrophages, because these types of macrophages are expected to be present early after surgery and are the main sources of IL-1β and IL-6." (PMID 40526308, 2025). "A systematic review consolidates these findings: across dozens of studies, hernia surgery induces systemic oxidative and inflammatory stress measurable by MDA, TBARS, lipid hydroperoxides, TOS/TAS, GSH depletion, SOD activity loss, IL-6, TNF-α, CRP, and calprotectin." (PMID 41440470, 2025). "Hernia surgery was shown to increase CRP, IL-6 levels, leukocyte count, neutrophil count, IL-1 levels, IL-10 levels, fibrinogen, and α1-antitrypsin, and decrease lymphocyte counts and albumin during the first 24 postoperative hours." (PMID 36739352, 2023).
hyperaldosteronism (4 papers, 2015 to 2024). Overproduction of aldosterone by the adrenal glands, which may lead to hypokalemia and/or hypernatremia. "These evidences explain the current association of hyperaldosteronism and CRP, adipocytokine release of TNF-α, IL-6 & IL-23 as well as adhesion endothelial markers; ICAM and VCAM and p-selectin." (PMID 27478508, 2016).
hyperplasia (4 papers, 2013 to 2025). An abnormal increase in the number of cells in an organ or a tissue with consequent enlargement. "IL-6 is reported to stimulate keratinocyte proliferation and is therefore studied in diseases associated with epidermal hyperplasia and in wound healing." (PMID 24078775, 2013).
hyperreactivity (4 papers, 2016 to 2024). "Moreover, IL-1β, IL-6 and IL-23 are known to induce IL-17A production in Th17 cells and are thereby linked to airway hyperreactivity related to obesity." (PMID 27087690, 2016). "We measured BAL CCL11 (eotaxin, an eosinophil chemoattractant), IL-23p19, IL-6, CXCL2 (pro-neutrophilic mediators), CCL20 (a lymphocyte chemoattractant), and IL-13 (known to prime smooth muscle cells for airway hyperreactivity)." (PMID 31572383, 2019).
hypertensive nephropathy (4 papers, 2013 to 2025). Kidney damage that results from chronically elevated blood pressure; complications include glomerular damage resulting in proteinuria and hematuria. "Certain scholars reported that IL-6 was correlated with proteinuria in hypertensive nephropathy, suggesting that urinary protein and IL-6 levels were associated." (PMID 24137196, 2013). "Cytokines IL-1β, IL-6, and TNF-α play a significant role in the occurrence and development of hypertensive nephropathy." (PMID 27069492, 2016). "In elderly individuals with hypertensive nephropathy, elevated levels of NGAL, KIM-1, IL-18, TNF-α, IL-6, NF-κB, and FMO3 were observed, accompanied by reduced urinary TMAO concentrations and impaired renal function, as indicated by increased serum creatinine and decreased eGFR." (PMID 40978750, 2025).
idiopathic scoliosis (4 papers, 2011 to 2023). A scoliosis with no known cause. "We conducted a case-control study of eighty patients with idiopathic scoliosis (IS) and one hundred sixty healthy unrelated gender-matched controls trying to investigate the association between IS and the IL-6 promoter polymorphism at -174 position (rs1800795 G/C) in Bulgarian population." (PMID 26199858, 2015). "IL-6 gene could be considered as susceptibility and modifying factor of idiopathic scoliosis." (PMID 26199858, 2015). "Our study used identical technical approaches compared to other studies on genetics of idiopathic scoliosis and the role of IL-6 in the etiopathogenesis of the disease as amplification-restriction (PCR-RFLP) and statistical analysis of data with SPSS for Windows." (PMID 26199858, 2015). "Regarding the role of MMPs family in idiopathic scoliosis, there are some contradictory findings in the literature about the role of gene variants of IL-6 and MMP-3 and whether MMP-3 and IL-6 promoter polymorphisms constitute important factors for the genetic predisposition to idiopathic scoliosis." (PMID 21554726, 2011).
intracranial hypertension (4 papers, 2020 to 2022). A finding characterized by increased cerebrospinal fluid pressure within the skull. "Another group of experiments on animal models of intracranial hypertension showed that increased ICP was significantly associated with increased levels of cytokines, such as IL-6, IL-18, IL-1α and IL-1β." (PMID 36441671, 2022). "IL-6 also appears to be a robust marker of both neuroinflammation and intracranial hypertension in the setting of TBI, and injection of anti-IL-6 antibodies reduced the production of pro-inflammatory cerebral cytokines and improved motor functions in mice." (PMID 36232495, 2022). "Animal experiments reflect these interlinks at the molecular level, as intracranial hypertension augments the inflammatory response in ARDS, characterized by increased levels of TNFα, IL-6 and IL-1β, and microglial activation." (PMID 33163005, 2020).
Lassa fever (4 papers, 2017 to 2024). A viral hemorrhagic fever that is caused by the Lassa virus, which is transmitted by contact with infected rodents; it is characterized by fever, headache, malaise, myalgia, and hearing loss. "IL-6 is highly upregulated in fatally infected NHPs and in LASV-infected humans, and elevated levels of IL-6 in plasma is currently being considered as a third biological marker of lethal Lassa fever in addition to viremia (>3.3 logs/mL) and liver enzyme aspartate aminotransferase (AST) (150 IU/mL)." (PMID 28498311, 2017). "The IFNα and γ response, E2F target, IL6/JAK/STAT3, G2/M checkpoint, IL2/STAT5 and complement pathways were activated during Lassa fever, as shown by comparison with mock-infected animals, but this activation was more intense after Josiah LASV infection." (PMID 39652618, 2024). "Increased serum levels of IL-6 were reported in other cases of VHF, such as EVD and Lassa fever." (PMID 31357521, 2019).
Left atrial enlargement (4 papers, 2021 to 2026). Increase in size of the left atrium. "From an echocardiographic standpoint, chronically high IL-6 levels are related to left atrial enlargement and impaired atrial function." (PMID 41590667, 2026). "These rats also exhibited left atrial enlargement, pulmonary congestion, and elevated levels of atrial natriuretic peptide and inflammatory marker IL6." (PMID 38169715, 2023).